PRNP (prion protein (Kanno blood group))
Diseases named in the same sentence as PRNP in open-access papers (continued):
Sharing a sentence is not in itself a finding about the gene and the disease.
scrapie (continued). "Thus, although we identified some additional polymorphisms of PRNP, we could not identify their effects as we had no scrapie-affected sheep for analysis." (PMID 37888549, 2023). "In closing, primary passage bioassay into Tg338 (ovine PRNP) and TgElk (elk PRNP) mice produced unique transmission profiles for the isolates of CWD and scrapie prions used in this study." (PMID 27393736, 2016). "In this study we have used two TSE strains which target sheep of different PRNP genotypes: BSE (which has the widest known host range of any TSE strain) and SSBP/1 (which is a well characterised experimental scrapie source)." (PMID 26587837, 2015). "In contrast to the PRNP+/+ goats, none of the PRNPTer/Ter goats had clinical signs of scrapie or evidence of PrPSc accumulation at 1260 dpi, which confirms that the PRNPTer-mutation confer resistance against scrapie in animals without PrPC." (PMID 31924264, 2020). "We demonstrated that brain homogenates from mice transgenic for the ovine PRNP gene (tg338) could be used as a substrate for PMCA consistent with previous reports and that the PMCA products from two VRQ/VRQ ovine scrapie isolates infected tg338 mice." (PMID 23472112, 2013). "The lack of PrPSc in the cotyledons with PRNP genotype 240P/146S240P is consistent with the field observations on relative resistance to scrapie in goats with this PRNP genotype." (PMID 21284878, 2011). "The isolates/strains tested had distinct PRNP genotypes in both seed and substrate and whilst scrapie isolates could not be confirmed as distinct strains, the analysis of scrapie and BSE indicates rRRQ is capable of inhibiting multiple strains." (PMID 36859422, 2023). "The variation in the number of octarepeat units (PHGGGWGQ) in the PRNP gene is another genetic marker that can be used to study the susceptibility/resistance of cervids to CWD, like as been done in scrapie, BSE and CJD studies, but so far no variation has been found in cervids studies." (PMID 36945178, 2023). "Moreover, finding negative age-matched controls with the same PRNP genotype within the same scrapie-affected flocks is not possible since the disease attack-rate in these animals is close to 100%." (PMID 24450868, 2014). "In contrast, the PrPd conformer associated with the ovine scrapie strain, although sharing the same PrP amino acid sequence as the PrPd in ovine BSE, could not be amplified in any of the PRNP humanized mouse substrates but could be amplified in a sheep brain substrate." (PMID 19961689, 2009).
Alzheimer disease (100 papers, 2008 to 2026). A progressive, neurodegenerative disease characterized by loss of function and death of nerve cells in several areas of the brain leading to loss of cognitive function such as memory and language. "In this study, we report on the association between the PRNP M129V polymorphism and mild cognitive impairment and dementia, including Alzheimer’s disease, within the population-based Rotterdam Study." (PMID 32954288, 2020). "Tetracycline targets PRNP, linked to depressive disorder, Huntington disease-like 1 and Alzheimer’s disease." (PMID 31481665, 2019). "It has been reported that PRNP gene contributes the association between the methionine/valine (M/V) polymorphism and risk of Alzheimer disease." (PMID 24993133, 2014). "This disease was originally misdiagnosed as Alzheimer's disease before the advent of PrP immunohistochemistry and the subsequent identification of the A117V mutation by PRNP sequencing." (PMID 24086135, 2013). "Odds ratios for the association between Alzheimer's disease and PRNP codon 129 in different strata defined by APOE ε4 allele status (V129V genotype and V129 allele are taken as reference or non-exposed)." (PMID 21799773, 2011). "In a case-controlled protocol, we assessed the possible association between the PRNP 1368 polymorphism and either Alzheimer's disease (AD) or vascular dementia (VaD)." (PMID 19351416, 2009). "Interestingly, PRNP mutations have been reported in patients diagnosed with Alzheimer’s disease, dementia with Lewy bodies, Parkinson’s disease, and frontotemporal dementia." (PMID 36614069, 2022). "The prion protein (PRNP) gene is associated with prion diseases, whereas variants of the PRNP gene may also explain some cases of Alzheimer disease (AD) and frontotemporal dementia (FTD) in Caucasian populations." (PMID 27910931, 2016). "Recently, PRNP has been shown to mediate the toxicity of other pathological protein aggregates, including oligomers of the amyloid β (Aβ) peptide, which are associated with Alzheimer’s disease PRNP." (PMID 24993133, 2014). "Here, we describe a nonsense haplotype in PRNP associated with clinical Alzheimer's disease." (PMID 24958194, 2014). "Reports of somatic point mutations in presenilin 1 gene in a case of sporadic early onset Alzheimer's disease and in the PRNP gene in a sCJD case suggest that somatic point mutations in other coding positions in PRNP may also lead to sCJD." (PMID 22028931, 2011). "Earlier onset of Alzheimer's disease: risk polymorphisms within PRNP, PRND, CYP46, and APOE genes." (PMID 21034472, 2010). "PRNP: an alternative trigger for tau pathology in early-onset Alzheimer’s disease?" (PMID 35393555, 2022). "In contrast, our results do not indicate a role of the M129V polymorphism of the PRNP gene in dementia, including Alzheimer’s disease, nor in brain volume and hippocampal volume." (PMID 32954288, 2020). "Prion diseases and TDP-43 proteinopathies share the feature of protein aggregation, and there is some evidence that PRNP may have a role in Alzheimer's disease." (PMID 18657254, 2008). "A key hallmark of major neurodegenerative disorders—including Alzheimer’s disease (AD), amyotrophic lateral sclerosis (ALS), frontotemporal dementia (FTD), synucleinopathies and prion diseases—is the intracellular accumulation of aggregated proteins such as MAPT, TDP43, FUS, PRNP and SNCA." (PMID 41278186, 2025). "Two more sites were used as controls: one within the prion gene (PRNP) and another within ANK1, a gene whose hypermethylation has consistently been reported in Alzheimer’s disease (AD)." (PMID 32918118, 2020). "Odds ratios for the association between Alzheimer's disease and APOE ε4 carriers (vs. APOE ε4 non-carriers) among different strata defined by PRNP codon 129 genotypes." (PMID 21799773, 2011). "Similarly, a recent report on rapidly progressive Alzheimer's disease has found that both APOE and PRNP may modulate the phenotypic expression of the disease." (PMID 21799773, 2011).
transmissible spongiform encephalopathies (89 papers, 2005 to 2025). "A protocol of choice was identified and applied for the quantification of a polymorphism at codon 136 of the ovine PRNP gene that is associated with susceptibility to a transmissible spongiform encephalopathy in sheep." (PMID 21283808, 2011). "The pathogenic variants of PRNP gene encode for an abnormal prion protein, which is misfolded and also induces misfolding in normal prion proteins, leading to cell death and to a group of called “prion disorders” or “transmissible spongiform encephalopathies”." (PMID 40584247, 2025). "Cellular prion protein (PRNP) is a ubiquitous membrane glycoprotein whose abnormal self-replicating, misfolded form is widely believed to cause several central nervous system disorders, collectively known as Transmissible Spongiform Encephalopathies (TSE)." (PMID 21483752, 2011). "Cellular prion protein (PRNP) is a glycoprotein involved in the pathogenesis of transmissible spongiform encephalopathies (TSEs)." (PMID 21483752, 2011). "The Prion protein (PRNP/Prp) plays a crucial role in transmissible spongiform encephalopathies (TSEs) like Creutzfeldt-Jakob disease (CJD), scrapie and mad cow disease." (PMID 21042590, 2010).
neuroblastoma (74 papers, 2008 to 2025). Neuroblastoma (NB) is the most common solid, extracranial childhood tumor. "In neuroblastoma cells, IR activates ATM, causes JNK to be phosphorylated by TAK1 in a manner that then activates AP-1 transcription factor, which in turn increases the transcriptional activity of the PRNP promoter by interacting with AP-1 binding sites." (PMID 36980514, 2023). "Here, we used the human neuroblastoma cell line, SH-SY5Y, with a deletion of the human PRNP gene (SH-SY5YΔPRNP) and inserted instead the Ovis aries PRNP gene (V136-R154-Q171 [VRQ] variant)." (PMID 32606072, 2020). "Studies of human SH-SY5Y neuroblastoma cells transfected with human PRNP displayed a significantly dampened response (MX2 expression) to a low-level IFN-α stimulation, compared with untransfected cells that are virtually devoid of PrPC." (PMID 28651013, 2017).
fatal familial insomnia (63 papers, 2008 to 2025). Fatal familial insomnia (FFI) is a very rare form of prion disease characterized by subacute onset of insomnia showing as a reduced overall sleep time, autonomic dysfunction, and motor disturbances. "Autosomal dominant prion diseases of the central nervous system, including Gerstmann-Sträussler-Scheinker disease (GSS), Creutzfeldt-Jakob disease, and fatal familial insomnia, are caused by mutations in the PRNP gene." (PMID 41142443, 2025). "Fatal familial insomnia (FFI) is a prion disease that involves a mutation in codon 178 of the gene encoding the prion protein (PRNP)." (PMID 35990086, 2022). "Fatal Familial Insomnia (FFI) is a genetic form of prion disease caused by the PRNP variant c.532G>A (p.Asp178Asn, aka p.D178N) in cis with the c.385A (p.129M) polymorphism." (PMID 31953922, 2020). "Related conditions involving PRNP mutations include fatal familial insomnia and Gerstmann-Straussler-Scheinker syndrome." (PMID 29682384, 2018). "Different PRNP mutations are associated with distinct clinical and neuropathological phenotypes: genetic Creutzfeldt-Jakob disease (gCJD), fatal familial insomnia (FFI), Gerstmann-Sträussler-Scheinker (GSS) syndrome, PrP cerebral amyloid angiopathy (PrP-CAA) and PrP systemic amyloidosis." (PMID 26864450, 2016). "Single-nucleotide mutations or sequence expansions within the PRNP gene are the cause of genetic prion diseases such as familial Creutzfeldt-Jakob disease (fCJD), fatal familial insomnia (FFI), and Gerstmann-Sträussler-Scheinker (GSS) syndrome." (PMID 34737343, 2021). "Different PRNP mutations are associated with distinct disease subtypes, including genetic Creutzfeldt-Jakob disease (gCJD), fatal familial insomnia (FFI) and Gerstmann-Sträussler-Scheinker (GSS) syndrome." (PMID 32673372, 2020). "Fatal familial insomnia (FFI) is characterized by a specific mutation (PRNP D178M-codon 129M) together with selective thalamic degeneration (seen also in sporadic fatal insomnia), although PrP deposits can be detected in other brain regions." (PMID 26848654, 2016). "This led to the discovery that multiple inherited neurodegenerative diseases including fatal familial insomnia (FFI), genetic Creutzfeldt–Jakob disease (gCJD), and Gerstmann–Straussler–Scheinker syndrome (GSS), are caused by certain mutations in PRNP." (PMID 38392286, 2024). "PRNP mutations are associated with a wide range of clinicopathological entities, encompassing CJD, Gerstmann–Sträussler–Scheinker disease (GSS), and fatal familial insomnia (FFI)." (PMID 34324063, 2021). "Genetic prion diseases, representing 10–15% of cases, include genetic Creutzfeldt–Jakob disease (gCJD), Gerstmann–Sträussler–Scheinker disease (GSS) and fatal familial insomnia (FFI), all of which are linked to mutations in the PRNP gene." (PMID 33925126, 2021). "Gerstmann Sträussler Scheinker syndrome and fatal familial insomnia (FFI) are inheritable forms of the disease, linked to specific mutations in the PRNP gene encoding the prion protein, e.g., P102L and D178N in combination with methionine at codon 129, respectively." (PMID 32977678, 2020). "Genetic prion diseases, such as familial Creutzfeldt-Jakob disease (fCJD), Gerstmann-Sträussler-Scheinker syndrome (GSS), and fatal familial insomnia (FFI), are caused by a sort of mutations within human PrP encoding PRNP gene." (PMID 23671608, 2013). "Hereditary forms of human TSE in which mutations in the prion protein gene (PRNP) predispose to disease include fCJD, Gerstmann-Sträussler-Scheinker syndrome (GSS) and fatal familial insomnia (FFI)." (PMID 18925969, 2008). "Genetic forms are associated with mutations in the PRNP gene and comprise genetic/familial CJD (gCJD), familial fatal insomnia (FFI) and PrP- amyloidoses, which include Gerstmann-Sträussler-Scheinker disease (GSS), PrP-cerebral amyloid angiopathy (PrP-CAA) and PrP systemic amyloidosis (PrP-SA)." (PMID 34224311, 2021).
fatal familial insomnia (continued). "Fatal familial insomnia (FFI) is a rare, autosomal dominant prion disease caused by a mutation in the PRNP gene, leading to the misfolding of the cellular prion protein (PrPC) into its pathogenic form (PrPSc)." (PMID 41107634, 2025). "Inherited cases constitute approximately 10–15% of human PrDs and are closely associated with dozens of mutations in the PRNP gene, including genetic CJD (gCJD), fatal familial insomnia (FFI), and Gerstmann-Sträussler-Scheinker (GSS) syndrome." (PMID 38390431, 2024). "Genetic forms, caused by mutations in the gene PRNP encoding for PrPC, include familial CJD (fCJD), Gerstmann-Sträussler-Scheinker syndrome (GSS) and fatal familial insomnia (FFI)." (PMID 32327983, 2020). "Inherited forms of human prion disease also include fatal familial insomnia (FFI) and Gerstmann–Sträussler–Scheinker disease (GSS), caused by pathogenic mutations in the prion protein gene (PRNP) believed to predispose mutant PrPC to convert spontaneously to PrPSc." (PMID 26841849, 2016). "Second, genetic prion diseases, including familial CJD (fCJD), fatal familial insomnia (FFI), and Gerstmann–Sträussler–Scheinker syndrome (GSS), are caused by mutations of the PRNP gene, which increase the tendency for mutated PrPC to be misfolded into the abnormal PrPSc." (PMID 28596963, 2017). "PrD, which fall under the genetic aetiologies due to point mutations or octapeptide repeat insertions in the PRNP gene, includes familial CJD (fCJD), Gerstmann–Stäussler–Scheinker (GSS) and fatal familial insomnia (FFI) while sporadic CJD (sCJD) presents with disease aetiology from unknown origins." (PMID 35394216, 2023). "Thus, the up- and down-regulation of human PRNP expression appear to be critical for the pathogenesis of human TSEs, such as CJD and fatal familial insomnia (FFI)." (PMID 23967259, 2013). "There are other genetic human prion diseases (Fatal Familial Insomnia (FFI), and Gerstmann Sträussler Scheinker syndrome (GSS)) traditionally separated from gCJD on clinico-pathological grounds, but which are related by certain common core features and an underlying causal PRNP mutation." (PMID 20035629, 2009). "We selected three PRNP variants, which are also followed by amino acid substitutions (P102L, P105L, and D178N) and appear to be associated with susceptibility to various prion diseases such as Gerstmann-Sträussler-Scheinker disease (GSS) and fatal familial insomnia (FFI)." (PMID 18493311, 2008).
Creutzfeldt-Jakob disease (58 papers, 2008 to 2026). "Although genome-wide association studies (GWAS) have identified two potential risk loci, the only strong genetic risk factor for Creutzfeldt-Jakob disease has remained PRNP itself." (PMID 34705895, 2021). "PRNP encodes the prion protein PrPC, responsible for the neurodegenerative process in Creutzfeldt-Jakob disease and has been shown to influence the stability and assembly of microtubules." (PMID 33137126, 2020). "PRNP genotype also affects human susceptibility to kuru, and both iatrogenic and sporadic forms of Creutzfeldt-Jakob disease." (PMID 31717531, 2019). "For example, almost all genotyped cases of variant Creutzfeldt-Jakob disease, which were presumably due to consumption of prion-tainted beef, have been homozygous for methionine at polymorphic residue 129 of PRNP." (PMID 31717531, 2019). "Sporadic Creutzfeldt-Jakob disease (sCJD) cases are currently classified according to the methionine/valine polymorphism at codon 129 of the PRNP gene and the proteinase K-digested abnormal prion protein (PrPres) isoform identified by Western blotting (type 1 or type 2)." (PMID 32546613, 2020). "The clinical characteristics of genetic Creutzfeldt-Jakob disease (gCJD) with a V180I mutation in the PRNP gene (V180I gCJD) are unique: elderly-onset, gradual progression, sporadic fashion, and cortical oedematous hyper-intensity on diffusion-weighted MRI (DW-MRI)." (PMID 32178563, 2020). "Polymorphisms of the prion protein gene (PRNP) at codons 129 and 219 play an important role in the susceptibility to Creutzfeldt-Jakob disease (CJD), and might be associated with other neurodegenerative disorders." (PMID 19351416, 2009). "Sporadic Creutzfeldt-Jakob disease (sCJD) cases are currently subclassified according to the methionine/valine polymorphism at codon 129 of the PRNP gene and the proteinase K (PK) digested abnormal prion protein (PrPres) identified on Western blotting (type 1 or type 2)." (PMID 18389084, 2008). "This study aimed to assess the prevalence of APOE genotypes (ε2, ε3, ε4) and PRNP mutations (E200K, M129V) in the general population of Pakistan because of their association with RPDs, including Rapidly Progressive Alzheimer’s Disease (rpAD) and Creutzfeldt-Jakob Disease (CJD)." (PMID 39654135, 2024). "Genetic testing with evidence of PRNP gene mutation is available but is not very sensitive, as 85% of patients present with the sporadic type of Creutzfeldt-Jakob disease without genetic mutations." (PMID 39881893, 2024). "These diseases, which include CWD, scrapie in sheep and goats, bovine spongiform encephalopathy (BSE) in cattle, and Creutzfeldt-Jakob disease (CJD) in humans, are caused by misfolded, infectious conformations (PrPSc) of a host encoded (PRNP gene) cellular prion protein (PrPC; Prusiner 1982)." (PMID 36201049, 2023). "Although no mutations in the human PRNP gene were found in a study of patients with hereditary neuropathies, the alteration of PrP or its sequestration in aggregates could explain the development of peripheral neuropathy in patients suffering from Creutzfeldt-Jakob disease." (PMID 33180885, 2020). "PRNP codon 129 genotype has been shown to be a major factor influencing disease characteristics of Creutzfeldt-Jakob disease, but it has not been established if the same is true of vCJD, because previous vCJD infections in 129MV persons exposed to contaminated blood products have been asymptomatic." (PMID 32441626, 2020).